IGFBP3 (insulin like growth factor binding protein 3)
Diseases named in the same sentence as IGFBP3 in open-access papers (continued):
Sharing a sentence is not in itself a finding about the gene and the disease.
diabetes (57 papers, 2002 to 2025). "Recent publications have focused mainly on the role of IGF2BP2 and IGFBP3 variants in diabetes and cancer risk." (PMID 38468402, 2024). "Age (OR=1.082, 95%CI 1.030-1.136, P=0.002), FPG (OR=1.493, 95%CI 1.047-2.128, P=0.027), TSH (OR=1.493, 95%CI 1.002-2.225, P=0.049) and IGFBP-3 (OR=1.414, 95%CI 1.019-1.963, P=0.038) were independent risk factors for thyroid nodules in type 2 diabetic mellitus." (PMID 39444449, 2024). "Top downregulated genes included those previously associated with diabetes and obesity, such as Manf and Creld2 that facilitate protein folding, and Igfbp3 and Igfbp7, two structurally similar proteins that regulate the bioavailability of IGFs and insulin." (PMID 36988733, 2023). "In support of this view, tear levels of IGFBP-3 are increased in patients with diabetes and this increase correlates with loss of the subbasal nerve plexus." (PMID 32194500, 2020). "IGF related proteins including IGF-I and IGFBP-3 have also been implicated in risk of human diseases including cardiovascular diseases and diabetes." (PMID 33152005, 2020). "Diabetes-induced changes in growth factor binding protein 3 (IGFBP-3) and tumor necrosis factor alpha (TNFα) have been linked to decreased insulin receptor signaling in diabetic retinopathy." (PMID 24695399, 2014). "To clarify the association between IGF-I or IGFBP-3 and renal dysfunction we used logistic regression models adjusted for age, waist circumference and type 2 diabetes mellitus." (PMID 23237568, 2012). "Notably, IGF-1 and IGFBP-3 have been implicated in developing thyroid nodules in patients with type 2 diabetes mellitus." (PMID 39444449, 2024). "In conditions such as hypoxia and hyperglycemia, the expression of IGFBP-3 is amplified, a phenomenon also noted in the tears of individuals with diabetes, where it is associated with changes in the sub-basal nerve plexus and the basal layer of corneal epithelial cells." (PMID 38276493, 2023). "In contrast, high serum IGFBP3 concentrations appear to have protective effects against cancer but have been shown to be associated with diabetes, high triglyceride levels and hypertension, whereas low IGFBP3 levels are associated with a large waist circumference and low levels of HDL cholesterol." (PMID 30759961, 2019). "In addition, epidemiological studies have found a positive association between the risk of developing type 2 diabetes mellitus and circulating IGFBP3 concentrations, with some evidence that these effects are independent of IGF1." (PMID 29947889, 2018). "The growth hormone/insulin‐like growth factor (IGF) axis can be manipulated in animal models to promote longevity, and IGF‐related proteins including IGF‐I and IGF‐binding protein‐3 (IGFBP‐3) have also been implicated in risk of human diseases including cardiovascular diseases, diabetes, and cancer." (PMID 27329260, 2016). "The present study investigated the potential of the IGF-1/IGFBP-3 molar ratio as a predictor of thyroid nodules in patients diagnosed with type 2 diabetes mellitus." (PMID 39444449, 2024). "Suppressing IGFBP3 activity can protect β-cells, potentially delaying or preventing the onset of diabetes, making it a promising therapeutic avenue for diabetes treatment." (PMID 38962743, 2024). "Another study discovered that the increase in tear Igfbp3 levels in type 2 diabetes mellitus (T2DM) patients correlated with damage to the corneal subbasal nerve plexus." (PMID 39769264, 2024). "Diabetes disrupts intestinal homeostasis through insulin-like growth factor binding protein 3 (IGFBP3)." (PMID 39682729, 2024). "In the context of diabetes, the dysregulation characterized by heightened basal IGFBP-3 and diminished SIRT1 (Sirtuin 1) levels contributes to compromised corneal epithelial healing." (PMID 38276493, 2023).
diabetes (continued). "IGFBP3/TMEM219 blockade with ecto-TMEM219 prevented the onset of diabetes in nearly 75% of treated mice (up to 80%), while only 25% of control mice were protected from diabetes in the untreated group." (PMID 35115561, 2022). "The observation that IGFBP3 levels are increased in patients with T1D or T2D and in those at risk for developing diabetes, as well as in pre-diabetic and diabetic mice, suggests a dysregulation of the IGFBP3/TMEM219 pathway in the context of diabetes." (PMID 35115561, 2022). "The IGF/IGF-IR-independent actions of IGFBP-3 have been shown to contribute to the pathophysiology of various human diseases such as cancer, diabetes, obesity, fatty liver disease, ischemia, and Alzheimer’s disease." (PMID 32443727, 2020). "In agreement with this latter finding, we have reported that human tear levels of IGFBP-3 are similarly increased in patients with diabetes." (PMID 32194500, 2020). "IGFBP-3 is a multifunctional protein and is involved in the pathophysiology of a variety of human diseases such as cancer, diabetes, fatty liver disease, ischemia, and Alzheimer’s disease." (PMID 32443727, 2020). "In particular, IGF/IGF-IR-independent actions of IGFBP3 have been shown to contribute to the pathophysiology of a variety of human diseases, such as cancer, diabetes, and Alzheimer’s disease." (PMID 29482621, 2018). "It is confirmed that increases in IGFBP-3 expression due to diabetes would attenuate the cellular response to IGF-1 through the high affinity binding of IGF-1 to IGFBP-3." (PMID 26823979, 2016). "We recently demonstrated that IGFBP-3 knockout mice have neuronal characteristics of diabetes and that IGFBP-3 and TNFα have antagonistic actions on apoptosis in retinal endothelial cells." (PMID 24695399, 2014). "We have previously reported that another protein, IGFBP-3, is reduced in response to diabetes, in correlation with the observed increase in TNFα." (PMID 25073020, 2014). "Two months after initiation of streptozotocin-induced diabetes, rats received a single intravitreal injection of IGFBP-3 NB plasmid in the right eye." (PMID 24695399, 2014). "Though there are conflicting reports about the effect of obesity on IGFBP-3 proteolysis it is evident that IGFBP-3 proteolysis is increased in patients with non insulin-dependent diabetes mellitus." (PMID 23383064, 2013). "The aim of the present study was to investigate the association between intra-prostatic levels of IGF-1, IGF-2 and BPH, as well as to evaluate the role of locally expressed IGFBP-3 in BPH development in different states of pre-diabetes." (PMID 24367483, 2013). "After adjusting for age, waist circumference and type 2 diabetes mellitus, analysis of variance (ANOVA) revealed inverse associations between serum IGF-I concentrations and eGFR in men as well as between serum IGFBP-3 concentrations and eGFR in men and women." (PMID 23237568, 2012). "The increased hepatic production of IGFBP3 observed in vitro upon exposure to either T1D or T2D serum and the abrogation obtained by targeting the pro-inflammatory microenvironment further suggest a common path of dysregulation for the IGFBP3/TMEM219 axis in diabetes." (PMID 35115561, 2022). "As TMEM219 is expressed on islet beta cells, we next assessed whether peripheral levels of TMEM219 ligand IGFBP3 were altered in patients with diabetes." (PMID 35115561, 2022). "It has been reported that the IGF-I/IGFBP-3 ratio can be used as an important indicator for the effect of growth hormone treatment in children, but there are limited studies conducted in conditions such as metabolic abnormalities and diabetes." (PMID 34239560, 2021).
diabetes (continued). "Previous studies provided evidence for the direct involvement of IGFBP-3 in metabolic disorders, as increased IGFBP-3 fragments in circulation have been observed in catabolic states such as diabetes and obesity, leading to a decrease in total IGFBP-3 concentration." (PMID 34239560, 2021). "IGFBP-1, IGFBP-3, IGFBP-4 are closely associated with diabetes and diabetic nephropathy." (PMID 35002740, 2021). "However, when we also adjusted for baseline levels of BMI, diabetes, and depression, higher levels IGF-1 and IGFBP-3 were still significantly related to a lower risk of frailty progression." (PMID 28609827, 2017). "Taken together, these data strongly suggest that IGFBP-3 shRNA could antagonize downregulation of the NO-cGMP signaling and ameliorate diabetes-related ED." (PMID 27136480, 2016). "Therefore, the aim of the present study was to investigate the association between intra-prostatic levels of IGF-1, IGF-2 as well as to evaluate the role of locally expressed IGFBP-3 in BPH development in pre-diabetes." (PMID 24367483, 2013). "In sub-analyses, we examined whether the association of IGF-I, IGFBP-3, or IGF-I/IGFBP-3 with pancreatic cancer was modified by sex, smoking status, length of follow-up, waist circumference, diabetes status, or circulating C-peptide concentration." (PMID 22315049, 2012). "Two diabetes related genes, coding for insulin-like growth factor (IGFBP3) and urotensin 2 (UTS2), were increasingly expressed with age which might indicate inclination of some individuals towards the development of type 2 diabetes." (PMID 22253695, 2012). "As shown, inversely correlated with serum IGF-I were age (P=0.03), alcohol intake (P=0.04), and having diabetes (P=0.03), whereas body weight and IGFBP-3 were positively associated with IGF-I levels (P<0.01), with IGFBP-3 and IGF-I having a moderately high correlation of r=0.69." (PMID 20717109, 2010). "IGFBP3/TMEM219 targeting may therefore serve as a therapeutic option in diabetes." (PMID 35115561, 2022). "Serum IGF-I and total IGFBP-3 levels were significantly higher in individuals with impaired glucose tolerance and type 2 diabetes (DM) than in those with normal glucose tolerance (NGT) (P < 0.05)." (PMID 34239560, 2021). "The duration of diabetes, age, FPG, FINS, TSH, IGF-1, IGFBP-3, and the serum IGF-1/IGFBP-3 molar ratio levels were independently associated with thyroid nodules in patients with T2DM." (PMID 39444449, 2024). "Consequently, the significant reduction in the expression of IGFBP-3 and IL-6, as a result of the inhibitory effects of these metabolites, leads to the emergence of abnormal blood glucose levels and the accompanying vasculopathy during the occurrence of diabetes in this study." (PMID 39206042, 2024). "The relevant influencing factors of DH included age, BMI, duration of diabetes, DPN, DR, DN, IGFBP-3, eGFR, and Scr." (PMID 36690699, 2023). "Pharmacological or genetic targeting of the IGFBP3/TMEM219 pathway successfully protects beta-cell mass, facilitates beta-cell expansion, and prevents and delays diabetes onset, suggesting a new therapeutic option for diabetic patients." (PMID 35115561, 2022). "In vitro and in vivo short-term IGFBP3/TMEM219 inhibition and TMEM219 genetic ablation preserved beta cells and prevented/delayed diabetes onset, while long-term IGFBP3/TMEM219 blockade allowed for beta cell expansion." (PMID 35115561, 2022). "Reduced IGFBP3 plasma levels and preserved islet morphology further confirmed the beneficial effect of ecto-TMEM219-mediated IGFBP3 inhibition in this diabetes model." (PMID 35115561, 2022). "In this new study the Authors demonstrated that the IGFBP3/TMEM219 pathway is a physiological regulator of pancreatic beta cell homeostasis and it is dysregulated in diabetes." (PMID 35115561, 2022). "We therefore interrogated the role of the IGFBP3/TMEM219 axis and its targeting in well-renown in vivo models of diabetes." (PMID 35115561, 2022).
diabetes (continued). "IGFBP-3, IGFBP-4, IGFBP-5, IGFBP-6 are involved in different kidney disease such as diabetes, FSGS and CKD physiological process as apoptosis proteins, IGFBP-7 has been used in clinical practice as a biomarker for early diagnosis and prognosis of AKI." (PMID 35002740, 2021). "Since diabetes leads to increased TNFα and decreased IGFBP-3, increased understanding of the interrelationship of TNFα and IGFBP-3 will likely lead to refined therapies that can promote IGFBP-3 actions, while inhibiting TNFα activities." (PMID 25073020, 2014). "The effect of diabetes on mRNA expression at each time point varied among IGF1R, IGFBP1, IGFBP2, and IGFBP3." (PMID 23878504, 2013). "It combines with insulin-like growth factor-I (IGF-I) to form a complex (IGF-I/IGFBP-3) that can treat growth hormone insensitivity syndrome (GHIS) and reduce insulin requirement in patients with diabetes." (PMID 24143239, 2013). "The complex (IGF-I/IGFBP-3) formed can be used to treat growth hormone insensitivity syndrome (GHIS) and reduce insulin requirement in patients with diabetes." (PMID 24143239, 2013). "Each of these genes has been proposed to be involved in angiogenesis or regulation of blood vessels; IGFBP3 and TGFB2 have also been proposed as genes related to diabetes." (PMID 21179236, 2010). "Conditions such as diabetes mellitus and liver cirrhosis may alter IGF-1 values by increasing the proteolysis of the IGF-1 binding protein 3 (IGFBP-3)." (PMID 37241010, 2023). "Overall, our findings demonstrate that the IGFBP3/TMEM219 pathway may serve as a physiological controller of beta cells and their lifespan, and that this pathway is dysregulated in diabetes." (PMID 35115561, 2022). "More importantly, the use of a newly generated recombinant protein based on the TMEM219 extracellular domain (ecto-TMEM219), which inhibits the IGFBP3/TMEM219 pathway, protected beta cells in vitro and prevented the onset of hyperglycemia in murine models of diabetes in vivo." (PMID 35115561, 2022). "The IGF-I-IGFBP-3 axis, especially IGFBP-3, may be involved in the pathogenesis and metabolic control of glucose intolerance, specifically in diabetes patients." (PMID 34239560, 2021). "We have also shown that IGFBP-3 and IGFBP-1 predict mortality and diabetes, respectively." (PMID 32492897, 2020). "Intravitreal injections of IGFBP-3 NB into the right eye of rats two months after the onset of diabetes significantly increased IGFBP-3 levels in the treated eye; no changes were observed in the untreated (left) eye." (PMID 24695399, 2014). "Also, in type 2 diabetes mellitus, the levels of IGF-1, IGFBP-3 and IGFBP-1 may be extremely variable." (PMID 39444449, 2024). "Although IGF1, IGFBP3, and IGFALS may be associated with diabetes, the levels of these proteins in our study in severe patients without diabetes were also very low, indicating that their decline was not only due to diabetes." (PMID 35958562, 2022). "However, in long-term normoglycemic NOD mice, which represent ~20–30% of female NOD mice that are normoglycemic at 26–30 weeks of age and do not develop diabetes, and in NOR mice resistant to diabetes, peripheral IGFBP3 levels were not increased." (PMID 35115561, 2022). "Thus, we believe that the IGF-I-IGFBP-3 axis, especially IGFBP-3, could serve as a useful therapeutic target for the treatment of diabetes." (PMID 34239560, 2021). "Increased expression of EPO and IGFBP3 and increased VEGF protein levels may be protective responses to damage caused by diabetes, but these responses may not provide sufficient protection." (PMID 23878504, 2013). "As an important growth factor, IGFBP-3 has been reported that it is highly correlated with erectile function in diabetic rat model and the increased expression of IGFBP-3 could elicit ED in patients with diabetes mellitus (DM)." (PMID 27136480, 2016). "Diabetes increased the expression of IGFBP2 after 12 weeks and IGFBP3 after 4 and 12 weeks, but did not change the expression of IGF1R or IGFBP1." (PMID 23878504, 2013).
colorectal cancer (55 papers, 2000 to 2025). A primary or metastatic malignant neoplasm that affects the colon or rectum. "High insulin levels stimulate the production of IGF-1 by liver cells after insulin binds to its receptor, whereas IGF-1 can also bind to insulin-like growth factor binding protein 3 (IGFBP-3), which is associated with a greater risk of colorectal cancer." (PMID 40457130, 2025). "Recent research from nearly 400,000 people in the UK Biobank using complementing serologic and Mendelian randomization analyses showed that levels of IGFBP3 predicted based on genetic factors were associated with colorectal cancer risk." (PMID 37764678, 2023). "Recent large prospective studies showed a strong correlation between low serum IGFBP-3 levels and increased colorectal cancer risk." (PMID 36430216, 2022). "In a similar manner, in colorectal cancer cells overexpression of miR-197 caused increased migration and invasion concomitant with downregulation of IGFBP-3 expression." (PMID 35597813, 2022). "Recently, IGFBP3 was found to be overexpressed in various tumor types and is not only associated with increased incidence in colorectal cancer but also leads to tumor metastasis by increasing cell migration and adhesion in nasopharyngeal carcinoma." (PMID 36131343, 2022). "The miR-197 levels in colorectal cancer tissues were inversely correlated with expression of IGFBP-3 and were associated with a more aggressive phenotype." (PMID 35597813, 2022). "High IGF1 levels and low concentrations of IGFBP3 are related to colorectal cancer and were significantly associated with liver metastasis, lymph node spread, and lymphovenous invasions." (PMID 34858769, 2021). "As an N‐linked glycosylated, phosphorylated and secreted protein, IGFBP3 has been demonstrated to inhibit cell proliferation and induce cell apoptosis of multiple common cancers, including prostate, breast, lung, and colorectal cancers." (PMID 31304688, 2019). "Accordingly, methylation of the IGFBP3 gene and low IGFBP3 expression occur frequently in aggressive colorectal cancer and are associated with poor response to adjuvant chemotherapy." (PMID 25374561, 2014). "Meanwhile, 4 studies evaluated the relationship between IGFBP3 Gly32Ala polymorphisms and colorectal cancer and included 1711 cases and 2995 controls." (PMID 23527244, 2013). "Although we have put considerable effort and resources into testing the possible association between IGFBP3 polymorphisms and colorectal cancer risk, there are still some limitations inherited from the published studies." (PMID 23527244, 2013). "The aim of this study is to explore the association between IGFBP3 A-202C and Gly32Ala polymorphisms and colorectal cancer susceptibility using meta-analyisi." (PMID 23527244, 2013). "The association between IGFBP-3 polymorphisms and colorectal cancer remains controversial and ambiguous." (PMID 23527244, 2013). "From 39 publications identified by initial data searches, nine studies examining the association of IGFBP3 -A202C and Gly32Ala polymorphisms with colorectal cancer were identified." (PMID 23527244, 2013). "Case-control studies on the association between IGFBP3 A-202C and Gly32Ala polymorphisms and colorectal cancer, which had sufficient data for estimating an odds ratio (OR) with 95% confidence interval (CI), were included in the meta-analysis." (PMID 23527244, 2013). "The plasma concentrations of IGF-1 and IGF binding protein-3 (IGFBP-3) were reported to influence the risk of colorectal cancer in a prospective cohort of 14,916 men." (PMID 23304125, 2012). "In our study associations between IGF-1, the molar IGF-1/IGFBP-3 ratio and C-peptide and colorectal cancers were similar for men and women." (PMID 22216097, 2011). "Epidemiological studies support an association between elevated circulating levels of IGF-I and reduced IGFBP-3 levels in the circulation and increased risk of breast, prostate, and colorectal cancer or adenoma." (PMID 18498652, 2008).